WNT1 (Wnt family member 1)
Diseases named in the same sentence as WNT1 in open-access papers (continued):
Sharing a sentence is not in itself a finding about the gene and the disease.
paroxysmal dyskinesia (1 paper, 2013). Paroxysmal dyskinesia (PD) is a rare heterogenous group of movement disorders manifesting as abnormal involuntary movements that recur episodically and last only a brief time. "In contrast, a sharp increase of firing rates was observed intermittently (about once/10 s) in Wnt1-Cre;Itpr1flox/flox mice and was tightly coupled to body movement related to paroxysmal dyskinesia." (PMID 24109434, 2013).
Patent ductus arteriosus (1 paper, 2022). In utero, the ductus arteriosus (DA) serves to divert ventricular output away from the lungs and toward the placenta by connecting the main pulmonary artery to the descending aorta. "We found a highly penetrant (9/14) patent ductus arteriosus (PDA) exclusively in SrfaI/flox; Wnt1-CreTg/+ neonates." (PMID 35044299, 2022).
postmenopausal osteoporosis (1 paper, 2025). Metabolic disorder associated with fractures of the femoral neck, vertebrae, and distal forearm. "In prior WNT1 patients, teriparatide treatment has been described to increase BMD and bone turnover markers, but to lesser extent than in postmenopausal osteoporosis." (PMID 41128774, 2025).
Progressive pseudorheumatoid dysplasia (1 paper, 2023). "Progressive pseudorheumatoid dysplasia (PPRD) is a rare autosomal recessive genetic disease caused by mutations in the Wnt1-inducible signaling pathway protein 3 gene." (PMID 37417608, 2023).
pulmonary hypertensive (1 paper, 2011). "Expression of Wnt ligands (Wnt1, Wnt3a, and Wnt5a) and Wnt signaling upstream regulator genes (Frizzled1 and 2 receptors and sFRP-1) and intracellular effectors (Axin1 and GSK3β) were investigated in pulmonary hypertensive rat lungs, 3 and 5 weeks after MCT injury." (PMID 21533110, 2011).
rectal tumors (1 paper, 2015). "The Wnt3 has been reported in the HepG2 (liver), A549 (lung), MKN45 (gastric), breast and rectal tumors, and it belongs to the Wnt1 class of ligands and canonical Wnt/β-catenin pathway." (PMID 26498690, 2015).
respiratory failure (1 paper, 2014). The significant impairment of gas exchange within the lungs resulting in hypoxia, hypercarbia, or both, to the extent that organ tissue perfusion is severely compromised. "We found that all Jmjd3f/f:Wnt1-Cre newborn pups died within 8 h of respiratory failure." (PMID 25079229, 2014).
rheumatoid arthritis (1 paper, 2024). A chronic, systemic autoimmune disorder characterized by inflammation in the synovial membranes and articular surfaces. "For example, miR-145-5p attenuates rheumatoid arthritis by inhibiting the Wnt1/beta-catenin signaling pathway." (PMID 39039505, 2024).
salivary gland tumors (1 paper, 2020). "An increased expression of the WNT1 gene led to an increased incidence of breast and salivary gland tumors in mice." (PMID 33227073, 2020).
schizophrenia (1 paper, 2012). A major psychotic disorder characterized by abnormalities in the perception or expression of reality. "It is intriguing that Wnt1, Fz3 and GSK3β – major Wnt/β-catenin pathway signalling components – have also been associated with schizophrenia or susceptibility to schizophrenia." (PMID 22615875, 2012).
squamous cell carcinoma (1 paper, 2025). A carcinoma arising from squamous epithelial cells. "One mouse developed squamous cell carcinomas, which had never been seen before in SPF Wnt1-transgenic mice." (PMID 39969175, 2025).
type 2 diabetes (1 paper, 2010). "It is interesting to note that TCF4, a transcription factor, coded by TCF7L2, the most strongly associated and replicated type 2 diabetes susceptibility loci, is an integral part of Wnt-1 signaling." (PMID 20625434, 2010).
uremia (1 paper, 2021). A clinical syndrome associated with the retention of renal waste products or uremic toxins in the blood. "The regulation of Wnt/β-catenin such as Wnt1, Wnt4 and β-catenin and PI3K/AKT pathways by adiponectin contributes to the improvement of VC in patients with uremia." (PMID 34398360, 2021).
tumor (308 papers, 2003 to 2025). "For example, miR-148a and miR-148b, which modulate Wnt1/β-catenin signaling, are associated with tumor suppression in HCC." (PMID 40943055, 2025). "LINC00665 activates WNT1 by binding to the WNT1 promoter, leading to M2 polarization of tumor-associated macrophages and promoting GC progression." (PMID 38952556, 2024). "We discovered that the levels of WNT-1 and mTOR expression in the cellular compartments were associated with tumor grade and staging." (PMID 37176048, 2023). "In contrast to membranous WNT-1, cytoplasmic and nuclear localizations were positively associated with higher tumor grade." (PMID 37176048, 2023). "In BRC, the TGIF1 upregulation is associated with poor prognosis and promotes the Wnt1-driven tumor progression." (PMID 38067260, 2023). "Exposure to estrogen has been associated with accelerated tumor formation in ER-knockout/Wnt-1 mice." (PMID 35418701, 2022). "There is an association between high Wnt1 expression in ccRCCs, increased tumor diameter, and more advanced stages." (PMID 36284630, 2022). "Despite the initial expression of Wnt1 by bipotent progenitor cells, these produce basal and luminal cells with luminal tumour cells expressing Wnt1, while basal and luminal cells gained HRas mutations." (PMID 33824479, 2021). "Previous studies have shown that Wnt/β-catenin signaling promoters such as Wnt1, Wnt2 and Wnt3a are associated with tumor proliferation and angiogenesis in NSCLC." (PMID 34465343, 2021). "In the current study, we explored the contributions of the infiltrated dendritic cells insulted by Wnt1 in tumor microenvironment to neuropathic pain associated with cancers." (PMID 32434423, 2020). "MiRNA-122 has been found to target a number of genes linked with tumour progression, including Snail 1 and Snail 2, WNT1, CREB1, and BCL9." (PMID 31979312, 2020). "In ccRCCs, high Wnt1 was associated with increased tumor diameter, stage and vascular invasion (p ≤ 0.02)." (PMID 23708097, 2013). "Intratumoral injection of anti-Wnt-1 antibody suppressed in vivo tumor growth in a Huh7 xenograft model, which was also associated with apoptosis and reduced c-Myc, cyclin D1, and survivin expressions." (PMID 19778454, 2009). "Moreover, both the FEO and FEO-CSNPs downregulated WNT1, a gene linked to accelerated tumor growth and poor prognosis." (PMID 40284420, 2025). "Thus, we examined lung sections of these mice at later time points when primary tumors reached similar size as that of Ctrl-Wnt1 tumors in 5 weeks to alleviate differences caused by varying primary tumor burden." (PMID 32493400, 2020). "This tumor-initiating property might be linked to the presence of Hras1 mutations in Wnt1-LateEx tumors." (PMID 31213486, 2019). "If similar synergy occurs in Wnt1-LateEx tumors, these activating Hras1 mutations might help to explain why these tumors have tumor-initiating potential." (PMID 31213486, 2019). "Interestingly, 10 of the 13 Wnt1-LateEx tumors profiled contained either codon 12 (1 tumor)- or codon 61 (9 tumors)-activating Hras1 mutations, whereas none of the Wnt1-EarlyEx tumors was mutated (Fisher's exact test P-value=0.0004)." (PMID 31213486, 2019). "Since tumor incidence was not significantly affected by partial SAFB1 loss, we asked whether loss of one SAFB1 allele would result in accelerated rates of tumor growth, as has been described for other models such as p21+/-/Wnt-1." (PMID 19267898, 2009). "As with many developmental genes, it was the recognition that tumours were caused by inappropriate Wnt-1 expression in many cases of mouse mammary tumour virus disease which focused attention on the fundamental role of Wnts in development, control of cell proliferation and differentiation." (PMID 18452624, 2008).
tumor (continued). "Wnt1-transgenic females in both housing conditions primarily developed adenocarcinomas, the archetypal tumor type characteristic of this model." (PMID 39969175, 2025). "We further analyzed microbial taxa that were significantly altered by alcohol exposure in adolescent Wnt1 mice, because they were more sensitive to alcohol’s tumor promotion compared to adults." (PMID 40740867, 2025). "Neutralization of this protective function of miRNA 152 is mediated by the HCV capsid protein, which negatively regulates miRNA 152 expression and activates the Wnt1 pathway, thereby inducing tumor cell proliferation." (PMID 41465470, 2025). "WNT1 is now well established in the regulation of tumor cell migration and epithelial-mesenchymal transition." (PMID 38191906, 2024). "In HNSCC xenograft and mouse mammary tumor virus (MMTV)-driven Wnt1 and Wnt3 tumor models, daily injections of LGK974 led to significant tumor regression." (PMID 38612911, 2024). "Expression levels of WNT-1 and mTOR were analyzed in the plasma membrane, cytoplasm, and nucleus of the tumor cells, and tumor grade was evaluated using H&E staining." (PMID 37176048, 2023). "In the 5a‐D‐Luc‐ZsGreen‐Wnt1 bone metastasis model, tumor cells invaded the diaphysis and formed osteoblastic tumors." (PMID 37840014, 2023). "The percentage of tumor cells exhibiting localization of WNT-1 in the plasma membrane decreased with an increase in tumor grade, whereas nuclear localization showed a slight increase with tumor grade." (PMID 37176048, 2023). "On the other hand, nuclear mTOR can be used for the confirmation of grade 3 neoplasms, as it has higher specificity (77.5%) than WNT-1." (PMID 37176048, 2023). "Comparison of our data with these studies revealed that our results were more similar to those observed in the Wnt1 early tumor stage than Wnt1 late tumors." (PMID 37243196, 2023). "WNT1 not only accelerates the proliferation of tumors by upregulating c-Myc, but also promotes the tumor malignant proliferation and angiogenesis by inducing the expression of target genes such as Cyclin D1, VEGF-A, and matrix metalloproteinase 7 (MMP7)." (PMID 37486552, 2023). "Ligands of the WNT canonical pathway, such as WNT1 and WNT10A, are associated with tumor progression, poor prognosis, and tumor invasiveness in ccRCC patients by oncogene activation, such as c-Myc and cyclin D1." (PMID 36910160, 2023). "The expression levels of WNT-1 in the plasma membrane of tumor cells tended to be lower in FIGO stage IB–IV tumors than in FIGO stage IA tumors." (PMID 37176048, 2023). "In order to further prove that NE can regulate the expression level of WNT7A, we detected the expression levels of Wnt1, Wnt2, Wnt3a, Wnt4, Wnt5a, Wnt6, Wnt7a and Wnt10a in tumour tissues of anti-PD-1 mAb + Vehicle and NE + anti-PD-1 mAb + Vehicle groups." (PMID 36646807, 2023). "ROC curves were drawn to determine the sensitivity and specificity of WNT-1 and mTOR expression in different cellular compartments as indicators of high tumor grade." (PMID 37176048, 2023). "Positive correlations were found between FJX1 expression and tumor-associated macrophages (TAMs) and with immune-related genes such as TGFB1 and IL-10 and immunosuppressive pathway-related genes such as TGFB1 and WNT1." (PMID 37324001, 2023). "The Wnt1 gene expression pattern was then compared among all the twelve normal, tumor and metastatic tissue samples as provided in the TNM dropdown list using gene chip data." (PMID 36056132, 2022). "Once tumors formed, tumor growth was significantly increased in K8iKOR-Wnt1 compared to control Wnt1 tumors." (PMID 36568144, 2022). "We found borderline significance between lower WNT1 expression in male patients (P=0.07) and stage II tumor versus stage I (P=0.06)." (PMID 36452484, 2022).
tumor (continued). "The co-expression of P-cadherin and E-cadherin and a partial EMT phenotype in IGF1R-reduced Wnt1 tumors suggests increased metastatic properties of these tumor cells." (PMID 36568144, 2022). "Wnt1 control, DN-Wnt1 and K8iKOR-Wnt1 tumor cells were plotted together resulting in 17 separate tumor cell populations." (PMID 36568144, 2022). "Adherence was decreased in DN-Wnt1 and K8iKOR-Wnt1 compared to Wnt1 primary tumor epithelial cells in vitro." (PMID 36568144, 2022). "We have also observed differential Wnt1 gene expression pattern in normal, tumor and metastatic conditions across different tissues." (PMID 36056132, 2022). "This borderline significance suggests that increased WNT1 expression occurs at earlier stages of carcinogenesis, which then decreases as the tumor grows." (PMID 36452484, 2022). "It was observed that Wnt1 gene was upregulated during tumor formation of endometrium, vulva, ovary and skin; although this upregulated expression was not statistically significant." (PMID 36056132, 2022). "Wnt1/FGFR1 mice showed significantly enhanced myeloid-derived tumor suppressor cells (MDSC) infiltration and tumor angiogenesis compared to single Wnt1 transgenic mice." (PMID 36147913, 2022). "We have compared the expression of Wnt1 gene in normal and tumor samples across 21 different tissues (as available in TNM dropdown list)." (PMID 36056132, 2022). "The first one, Wnt1, initially called Int1, was identified 40 years ago as an oncogene activated by mouse mammary tumor proviral DNA at the Wnt1 locus, resulting in mammary tissue hyperplasia and tumor formation." (PMID 35158896, 2022). "The mean tumor latency of Wnt1 mice was consistent with previous reports, where 50% of control Wnt1 animals formed palpable tumors at 41.7 weeks of age." (PMID 36568144, 2022). "Among the genes of this episignature, we confirmed the hypermethylation of WNT1 in cfDNA and tumor tissues (primary and metastatic) as a potential new biomarker for LBBC patients." (PMID 36393855, 2022). "Wnt1 tumors have been divided into two subtypes with distinct gene expression (ex) profiles: Wnt1-early(ex) and Wnt1-late(ex), which correlate with early (average 6.5 weeks) and late (average 22.5 weeks) tumor onset respectively." (PMID 35302059, 2022). "The Wnt1 gene expression in different cancer types revealed its importance in tumor progression and cancer formation." (PMID 36056132, 2022). "HIF1-α, VEGF, Cyclin D1, Wnt1, and β-catenin expression in the tumor was detected by Western blotting." (PMID 35711625, 2022). "It is also interesting that in our prior study we showed that Wnt1 tumor epithelial cells increase tumorsphere formation frequency in non-adherent conditions after IGF1R inhibition." (PMID 36568144, 2022). "Enrichment analysis was performed by comparing genes reported to be upregulated in normal mammary stem cells with genes differentially expressed in HER2/neu or Wnt1 residual tumor cells compared to primary and recurrent tumors cells." (PMID 34088357, 2021). "One of the most important functions of WNT1 is to inhibit cell apoptosis by increasing the invasiveness of cells and promoting the growth of blood vessels, thereby participating in tumor formation." (PMID 32898953, 2021). "By inhibiting the expression of SOX2 in lung cancer, the expression of Wnt1/2, Notch1 and c-myc genes can be down-regulated and tumor cell apoptosis can be induced." (PMID 34135756, 2021). "Together, our findings in both HER2/neu and Wnt1 models that tumor cells surviving oncogenic pathway downregulation are quiescent, despite a richly vascularized, non-hypoxic microenvironment, suggest that these cells exist in a state of cellular dormancy." (PMID 34088357, 2021). "In transplanted tumor tissue, in comparison with control groups, WNT1, Cyclin D1, and c-myc mRNA expression was decreased in mimics group." (PMID 34657551, 2021).
tumor (continued). "Orthotopic primary tumors and MRLs were generated, as above, from H2B-eGFP-labeled HER2/neu-Prim1 or Wnt1-Prim1 tumor cells, and osmotic pumps were employed to deliver bromodeoxyuridine (BrdU) for 2 weeks prior to sacrifice." (PMID 34088357, 2021). "Consistent with this, we found that inhibition of miR-34c in fibroblasts promoted the cell proliferation and migration in QBC939 cells, although WNT1 suppression restrained the effect of miR-34c on tumor progression, in vitro and in vivo." (PMID 34261453, 2021). "While miR-140-5p and miR-185 target Wnt1 and act as tumor suppressors, miR-410 targets Dkk1 and thus functions as an oncogene in CRC." (PMID 33585487, 2021). "In both the HER2/neu and Wnt1-driven models, residual tumor cells in which oncogene expression had been reactivated proliferated at rates similar to primary tumor cells, as measured by 2 h BrdU incorporation." (PMID 34088357, 2021). "H2B-eGFP-labeled HER2/neu-Prim1 or Wnt1-Prim1 tumor cells were used to generate orthotopic primary tumors, 28-day MRLs, and recurrent tumors." (PMID 34088357, 2021). "In contrast, both primary and residual tumor cells from Wnt1-induced tumors express epithelial markers characteristic of luminal and myoepithelial cells." (PMID 34088357, 2021). "LGK974 inhibits the expansion of the murine tumor xenograft model via ectopic Wnt1 expression originating from the mouse mammary tumor virus (MMTV)." (PMID 34135756, 2021). "An anti-Wnt1-antibody has been found to inhibit Wnt/β-catenin signaling and tumor growth in a xenograft mouse model." (PMID 33585487, 2021). "This revealed significant downregulation of mTOR pathway activity in both HER2/neu and Wnt1 residual tumor cells compared to their corresponding primary or recurrent tumor cells." (PMID 34088357, 2021). "As anticipated, primary tumor cells in both the HER2/neu and Wnt1 models expressed CK8, and a subset of Wnt1 tumor cells expressed CK14." (PMID 34088357, 2021). "For example, aspirin-induced miR-98 expression and long non-coding RNA (lncRNA) MIR503HG have been found to suppress proliferation of lung ADC and NSCLC cells via targeting Wnt1 and thus serve as tumor suppressors." (PMID 33585487, 2021). "Wnt1 is also highly expressed in HCC cell lines and has been associated with increased tumor recurrence after curative tumor resection in HBV- and HCV-related HCC patients." (PMID 33585487, 2021). "In order to identify genetic determinants directing tumor escape, a transgenic mouse model was employed, where targeted chemotherapy was simulated by blocking doxycycline-dependent Wnt1 transgene expression." (PMID 33445626, 2021). "Hh and Wnt pathways activation was assessed by immunohistochemistry (Gli1 and beta-catenin) on corresponding tumor tissues, and by plasma concentrations of Shh and Wnt (Wnt1, Wnt2 and Wnt3) at ICI introduction and at the first clinical evaluation." (PMID 33807552, 2021). "The decrease and ablation in FAK protein levels in cKD-Wnt1 and cKO-Wnt1 tumors, respectively, relative to Ctrl-Wnt1 tumors were further validated by immunohistochemical analysis of tumor sections from these mice." (PMID 32493400, 2020). "In vivo, pre-let-7c inhibited while anti-let-7c potentiated tumor growth and WNT1 and TCF-4 were downregulated in xenografts with pre-let-7c." (PMID 32641854, 2020). "We further evaluated the expression of Wnt1, β‐catenin, EMT markers (E‐cadherin and vimentin) and stemness‐associated markers (CD133, Nanog and Oct4) in xenograft tumours." (PMID 33026174, 2020). "TCF7L2, Wnt1 and β‐catenin (nuclear) protein expression increased in tumours overexpressing SPRY4‐IT1." (PMID 31736268, 2020). "Ipafricept (OMP-54F28) is a fusion protein that competes with native Fzd8 receptor for Wnts binding and blocks tumor growth in Wnt1-induced mice through antagonizing Wnt signaling." (PMID 32923386, 2020). "As a member of the Wnt family, Wnt1 has been shown to involve in tumor progression, adaptive immune resistance and bone remodeling." (PMID 32907622, 2020).